EGFR (epidermal growth factor receptor)
Diseases named in the same sentence as EGFR in open-access papers (continued):
Sharing a sentence is not in itself a finding about the gene and the disease.
lung cancer (continued). "Treatment with Icotinib significantly reduces the levels of p-EGFR (phosphorylated EGFR), p-ERK (phosphorylated extracellular signal-regulated kinase), and c-Cbl in HCC827 lung cancer cells, leading to inhibited proliferation and induced apoptosis of HCC827 lung cancer cells." (PMID 39048965, 2024). "Meanwhile, in NSCLC, the activation of PAR2 leads to the reactivation of EGFR, which promotes the epithelial–mesenchymal transition (EMT) process of lung cancer cells through the ERK signaling pathway and then promotes the proliferation and migration of NSCLC cells." (PMID 39308869, 2024). "The EGFR signaling pathway is deregulated in cancers, and EGFR and VEGF signaling has a major role in angiogenesis, tumor development, and metastasis, and dual inhibition of these signaling pathways is considered a potential strategy of lung cancer treatment." (PMID 38234663, 2024). "These two degraders displayed potent and selective antitumor activities in EGFR TKI-resistant lung cancer cells but not in normal cells." (PMID 39456995, 2024). "Prior research has shown that DUSP22 can inhibit the migration of H1299 lung cancer cells with wild-type EGFR by dephosphorylating FAK, a non-receptor tyrosine kinase." (PMID 38877005, 2024). "The fact that 80%–90% of lung cancer patients lack mutant EGFR and do not respond to currently available EGFR inhibitors motivates researchers to develop novel small molecule inhibitors that can effectively block both typical and mutant EGFR proteins." (PMID 39512829, 2024). "In people with and without disabilities, EGFR gene tests related to lung cancer and KRAS and NRAS gene tests related to colorectal cancer appeared as the top genetic test items among people aged ≥40 years." (PMID 38711356, 2024). "Both EGFR and NRF2 follow the same pattern of expression in lung cancer patients." (PMID 39026573, 2024). "Emerging evidence has revealed that in addition to EGFR TKI therapy failure, AST has also been observed in other molecular targeted therapy resistance of lung cancer, e.g. in lung cancer patients who have relapsed from ALK inhibitor treatment or KrasG12C inhibitor adagrasib treatment." (PMID 39687207, 2024). "To further demonstrate the specificity of the SH2-based biosensor BRET signals, we monitored the inhibitory action of Gefitinib (IressaTM), an EGFR-specific tyrosine kinase inhibitor (TKI), commonly used as a first-line treatment for some breast and lung cancers." (PMID 38429428, 2024). "AKT1, EGFR, and STAT3 were enriched in the non-small cell lung cancer (NSCLC) pathway according to Kyoto Encyclopedia of Genes and Genomes analysis, indicating a significant connection to lung cancer development." (PMID 38731403, 2024). "Additionally, our findings unveiled the capacity of the PHF12-HDAC1 axis to activate the EGFR/AKT signaling pathway, thereby further corroborating its significance in lung cancer progression." (PMID 39075515, 2024). "This discovery led to the development of drugs targeting mTOR (e.g., everolimus and temsirolimus) and EGFR-TKIs targeting EGFR and ALK (e.g., ositinib, gefitinib, ceritinib, and loratinib), which have demonstrated clinical efficacy in the treatment of lung cancer." (PMID 39391313, 2024). "The DNA probe is a popular method for lung cancer detection, for example, the ssDNA modified probe for CYFRA21-1 gene, ssDNA λ-exon-modified probe for EGFR, and primer probe for human maternally expressed gene 3 have been successfully developed for lung cancer detection." (PMID 38733011, 2024). "In lung cancer, MET can form heterodimers with RTKs such as EGFR, HER2, HER3, and RET." (PMID 39201787, 2024). "EGFR was identified as the primary target of DUSP22 in both HCC827 and H1650 lung cancer cells." (PMID 38877005, 2024). "In the future, whether to use EGFR inhibitors such as erlotinib (Tarceva®) and gefitinib (Iressa®) for targeting AREG and decreasing long-term exposure to PM-induced lung cancer patients is worthy of further study." (PMID 38904011, 2024).
lung cancer (continued). "Enforced DUSP22 expression significantly suppresses the growth of erlotinib-resistant H1650 lung cancer cell-based tumor by inhibiting EGFR and downstream ERK1/2 while not affecting sustained Akt activity." (PMID 38877005, 2024). "Most lung cancer patients with metastatic cancer eventually relapse with drug-resistant disease following treatment and EGFR mutant lung cancer is no exception." (PMID 38658677, 2024). "Furthermore, CUR effectively downregulated EGFR and STAT3 expression in lung cancer cells, suggesting its potential to disrupt key signaling pathways involved in tumor progression." (PMID 39508791, 2024). "Afatinib (EGFR/HER2-4 inhibitor) is used to treat EGFR-mutant-dependent lung cancer (it is not my case, as mine is METex14-dependent)." (PMID 39078370, 2024). "When combined with gefitinib, T0901317 reduced the migration and invasion levels of lung cancer via inhibition of the MAPK pathway, and sensitized the HCC cells towards sorafenib by inhibiting Mesenchymal-Epithelial Transition (MET) and EGFR." (PMID 38550382, 2024). "While early liquid biopsy approaches focused on single genes such as epidermal growth factor receptor (EGFR), these have rapidly been eclipsed by multigene assays, given the growing number of actionable biomarkers both at lung cancer diagnosis and for treatment resistance." (PMID 40027147, 2024). "Furthermore, lung cancer tissues exhibited higher expression levels of PIK3R1, AKR1C3, and EGFR when compared to normal lung tissues." (PMID 39204124, 2024). "Epidermal growth factor receptor tyrosine kinase inhibitors (EGFR-TKIs) recommended for the patients with subsolid nodule in early lung cancer stage is not routinely." (PMID 38528507, 2024). "EGFR status for lung cancer patients was not recorded in our study, although recent studies indicate improved treatment response for patients with EGFR mutation receiving TKIs." (PMID 38920717, 2024). "Both of these studies (63% of patients, 50/79) included patients with EGFR-mutant lung cancer, unlike any other studies in the NSCLC cohort." (PMID 39077464, 2024). "In lung cancer, TRIB3 has been reported to facilitate tumor progression by interacting with EGFR; Similarly, TRIB3 has been shown to enhance the stemness of cancer cells and drive the progression of colorectal cancer and glioma by interacting with β-catenin and TCF4." (PMID 39881875, 2024). "However, osimertinib which is a third-generation EGFR-TKI has been shown to be superior to erlotinib and gefitinib in a clinical trial AURA and FLAURA in lung cancer." (PMID 38699639, 2024). "Our cohort was comprised of 20 patients with EGFR-mutant tumors, two patients with ALK-driven tumors, and two patients with non-EGFR and non-ALK mutated lung cancer." (PMID 38806586, 2024). "Furthermore, the interaction between CPH with prominent lung cancer pathways such as KRAS and EGFR and their inhibitors should be further evaluated in lung cancer cell lines that show different sensitivity to KRAS inhibitors." (PMID 39522095, 2024). "Furthermore, we employed the same lightweight model to classify patient-derived lung cancer cells, both categorized as adenocarcinomas, with distinct genetic profiles: one harboring the KRAS oncogene (HCC 4087) and the other the EGFR oncogene (HCC 4190)." (PMID 39180048, 2024). "A 53-year-old woman undergoing combination therapy with epidermal growth factor receptor (EGFR) and vascular endothelial growth factor receptor (VEGFR) inhibitors for advanced lung cancer with brain metastases developed pustules and punctate purpura on both lower extremities." (PMID 39881923, 2024). "EGFR-driven cancers in never smokers showed a significant association of PM2.5 and the incidence of lung cancer in multiple cohorts." (PMID 39125735, 2024). "Additionally, cancer outgrowth images of two patient-derived lung cancer cells, one with the KRAS oncogene and the other with the EGFR oncogene, were captured and classified using the CNN model." (PMID 39180048, 2024).
lung cancer (continued). "EGFR signaling was identified as the dominant mechanism of resistance to KRAS G12C inhibitors in colorectal cancer rather than in non–small cell lung cancer." (PMID 39704172, 2024). "For instance, treating patients with wide-type EGFR lung cancer with cisplatin revealed that TKIs produced neither a synergistic nor an enhancing effect on platinum-based chemotherapy, with some evidence pointing to a possible antagonistic effect." (PMID 38982494, 2024). "It is important to note that ramucirumab has been shown to improve the efficacy of EGFR TKI erlotinib in EGFR-mutant NSCLC in the first-line setting, in line with the hypothesis of an angiogenesis dependency in EGFR-mutant lung cancers." (PMID 38473297, 2024). "Few prospective observational studies have assessed the clinical characteristics of patients treated (ICI group) and not treated (Non-ICI group) with ICIs in EGFR-mutant lung cancer." (PMID 38347279, 2024). "Dysregulated EGFR activation in the absence of proper physiologic signal plays a crucial role in oncogenesis and in maintaining the malignancy of lung cancer and therefore an ideal therapeutic target." (PMID 39041204, 2024). "It is not considered useful in ALK‐ and EGFR‐positive lung cancers because most are adenocarcinomas." (PMID 38400801, 2024). "Our previous study showed that ESM1 could directly bind to the extracellular domain (ECD) of the EGFR and enhance EGF binding, thereby increasing EGFR phosphorylation and downstream signal transduction in lung cancer." (PMID 39309430, 2024). "This evidence shows that TRIM29 is a link between EGFR and SLC7A5 in lung cancer cells." (PMID 37692503, 2024). "In this scenario, customized medicine has brought successful outcomes in drug selection for lung cancer patients with NSCLC based on the paradigms of their molecular profiles, specifically those with positive genetic alterations in EGFR, ALK, ROS-1, HER2, BRAF, MET, and RET genes." (PMID 39410578, 2024). "Furthermore, SOP-Phos-DIA demonstrated robustcoverage to reveal a complex interplay of Hippo signaling, EGFR-TKIsignaling, and ERBB signaling, which are likely involved in the TKI-resistancemechanism in lung cancer cells." (PMID 39038167, 2024). "In lung cancer, CD47 expression is associated with poor survival and tumors with EGFR mutations, which do not typically respond to PD-1 blockade." (PMID 37958404, 2023). "In lung cancer, CPNE1 acts as a target of miR-335-5p, and the inhibition of CPNE1 could enhance the clinical efficacy of EGFR-tyrosine kinase inhibitors." (PMID 37077419, 2023). "The 2016 Guideline for Treatment of Lung Cancer of The Japan Lung Cancer Society recommends testing patients with non-squamous NSCLC for multiple biomarkers, including EGFR gene mutation, ALK fusion, and programmed cell death 1 (PD-L1) expression." (PMID 37658334, 2023). "We do not know why these associations occurred in lung cancer, and no information about the interaction of FAF1 and EGFR has been reported thus far." (PMID 37999107, 2023). "Preclinical cases suggest that EGFR tyrosine kinase inhibitors (TKIs) plus MET TKIs are a potential therapy for non-classical EGFR mutant lung cancers with MET amplification acquired resistance." (PMID 36910616, 2023).
lung cancer (continued). "No clinical trials of EGFR-targeted NPs in lung cancer have been identified to date but three trials using anti-EGFR immunoliposomes containing Doxorubicin (anti-EGFR ILs-dox) were conducted for the treatment of other types of cancer." (PMID 37754880, 2023). "We here focused on mutant epidermal growth factor receptor (EGFR)-driven lung cancer, which is common in non-smokers or light smokers in East Asia." (PMID 37929799, 2023). "In addition, immunoblotting demonstrated that EGFR signaling and EMT related proteins (Vimentin and SNAIL) were considerably downregulated after PELI1 knockdown in these two lung cancer cell lines." (PMID 36841821, 2023). "Young lung cancer patients have a different profile, as many young lung cancer patients are never smokers, have actionable mutations (most common being ALK and EGFR), and have predominantly adenocarcinoma histology." (PMID 37700839, 2023). "Moreover, IHC analysis of 108 clinical lung cancer tissues revealed a significant decrease of JMJD5 and increase of EGFR level in tumors compared to adjacent tissues." (PMID 37813845, 2023). "Two groups of patients with non‐small cell lung cancer (NSCLC) who received or did not receive EGFR‐TKI were included and followed up for more than 24 months." (PMID 38054663, 2023). "The signal would identify both a type of cancer and hopefully some subtype of cancer (e.g., EGFR mutant lung cancer or basal bladder cancer) but would not offer a complete genome to sequence." (PMID 37169023, 2023). "Moreover, lnc-MLETA1 expression was positively correlated with EGFR and IGF1R expression in lung cancer tissues." (PMID 37880793, 2023). "Upon further analysis of the CCLE (Cancer Cell Line Encyclopedia)-RPPA, a negative correlation between P-AMPK and EGFR protein expression was found in lung-cancer cell lines." (PMID 37240137, 2023). "Amplification of Chr22q11 has been reported at low frequency in some malignancies; including lung cancer patients progressing to EGFR TKIs, although the finding was not confirmed in later studies." (PMID 37443114, 2023). "PM2.5 exposure from polluted air is the main risk factor for lung cancer in never-smokers, which predominately develops as ADC with EGFR driver-mutations in the peripheral lung." (PMID 37696458, 2023). "Recent studies reported that patients with EGFR/ALK/ROS1 mutation, bone metastasis, and no immune-related adverse events had poor prognosis during immunotherapy in lung cancer." (PMID 37790758, 2023). "CRISPR technology has been successfully applied to implement the editing and modulation of numerous oncogenes such as epidermal growth factor receptor (EGFR), KRAS, focal adhesion kinase (FAK), metabotropic glutamate receptor 8 (GRM8), SMAD3/4, and MET in lung cancer." (PMID 38188023, 2023). "Other clinical trials have focused on the development of new EGF/EGFR targeted therapies, such as monoclonal antibodies and TKI, which may provide patients with lung cancer with better therapeutic alternatives." (PMID 37760616, 2023). "These compounds strongly induced the degradation of the mutant but not the wild-type EGFR in cancer cell lines and effectively suppressed the growth of lung cancer cells." (PMID 37754201, 2023). "Consistent with this, preclinical data demonstrate that ibrutinib inhibits EGFR, HER2, and human epidermal growth factor receptor 3 (HER3) in breast cancer cell lines, and both EGFR (L858R) and EGFR (T790M) in mutant EGFR-expressing lung cancer cell lines." (PMID 37919668, 2023). "However, EGFR TKI resistance, as the Achilles’ heel of targeted therapy in lung cancer, almost invariably limits the clinical efficacy of targeted." (PMID 37951898, 2023). "ERCC5 may become a potential therapeutic target for the treatment of lung cancer patients, as important as HER2 and EGFR." (PMID 38137354, 2023).
lung cancer (continued). "Opioids may also induce cell proliferation and trigger epithelial‐mesenchymal transformation in lung cancer, and activation of MOR is also suggested to activate EGFR signaling pathways." (PMID 37706634, 2023). "Besides, EGFR has been recognized as an oncogenic driver of NSCLC, making it increasingly important in the era of precision medicine for lung cancer." (PMID 37841421, 2023). "Thus EGFR–KRAS signaling stabilizes PD-L1 protein, at least partially, by suppressing MTSS1 protein expression in lung cancer." (PMID 36810288, 2023). "Interestingly, our findings further support the notion that the EGFR pathway is instrumental in inducing anoikis of CTCs by polyphyllin VII, extending its relevance to lung cancer metastasis." (PMID 37928267, 2023). "Moreover, miR-186-5p and miR-497-5p expression was negatively correlated with expression of the target genes EGFR and IGF1R in lung cancer tissues, respectively." (PMID 37880793, 2023). "To explore this hypothesis, we designed an in vitro co‐culture assay of RBC from healthy donor and lung cancer cell lines (A549 with KRAS G12S and H1975 with EGFR L858R, T790M)." (PMID 36599687, 2023). "Furthermore, lung cancer patients with both elevated lnc-MLETA1 and EGFR or IGF1R displayed the worst survival, indicating the superior prognostic value of combining the two parameters compared with one gene alone." (PMID 37880793, 2023). "The epidermal growth factor receptor (EGFR), a transmembrane receptor tyrosine kinase, plays an important role in proliferation, differentiation, and survival and is involved in tumorigenesis, especially in lung cancer, breast cancer, and glioblastoma." (PMID 37229243, 2023). "Next, we investigated whether 8PN‐mediated CDCP1 reduction can increase the sensitivity to EGFR TKI in EGFR TKI‐resistant lung cancer cells, including H1650 (EGFR exon 19 deletion and PTEN mutant) and H1975 (EGFR L858R) cells." (PMID 37013960, 2023). "EMT may also drive resistance to targeted therapies such as EGFR inhibitors, as genetic silencing of TWIST1 sensitized EGFR-mutant lung cancer to osimertinib and erlotinib." (PMID 37954979, 2023). "Additionally, TUSC2 regulates multiple downstream EGFR targets, such as FGFR2, mTOR, AKT, and c-Abl in lung cancer." (PMID 37173921, 2023). "In addition, gefitinib’s inhibition of EGFR signaling decreased the expression of the PELP1 protein, whereas EGF’s stimulation of the EGFR pathway increased PELP1’s protein expression in lung cancer cells." (PMID 36909198, 2023). "EMT marker Twist knockdown induces caspase-3- and -7-dependent apoptotic cell death by inhibiting the phosphorylation of EGFR, Akt, vimentin, and Twist1, and by activating E-cadherin in EGFR-TKI gefitinib and AZD9291-treated gefitinib-resistant lung cancer cells." (PMID 36768961, 2023). "In contrast, the results of several clinical trials of EGFR-TKI combination immunotherapy showed no additional benefit in the treatment of lung cancer." (PMID 37901223, 2023). "In particular, EGFR, KRAS, CTNNB1, and ERBB2 genes were captured within the top 20% rank by at least four scRNA-seq workflows, and the two genes EGFR and KRAS, which were most common in lung cancer, were ranked in the top 5.4% and 8.9% by ZW_edgeR_Cov, respectively." (PMID 36944632, 2023). "One of the lung cancer brain metastases samples has been examined without rearrangements of ALK and ROS1 and EGFR mutation." (PMID 37479733, 2023). "Previous studies indicated that EGFR and IGF1R are essential in lung cancer progression." (PMID 37880793, 2023). "In addition, silencing of LAMC2 inhibited the oncogenic capacity of EGFR in lung cancer cells, suggesting that LAMC2 acts upstream of EGFR." (PMID 37542131, 2023). "In lung cancer, anoikis resistance could be overcome by NOX4 knockdown followed by reduced activation of Src and EGFR." (PMID 37091854, 2023).